OXT (oxytocin/neurophysin I prepropeptide)
Diseases named in the same sentence as OXT in open-access papers (continued):
Sharing a sentence is not in itself a finding about the gene and the disease.
Anxiety (continued). "It has been established that receptors of oxytocin (OXT) and arginine vasopressin (AVP) neuropeptides are distributed in different brain regions associated with central nervous system control of stress, anxiety and social behavior." (PMID 34805562, 2021). "We further found that the gestational stress-induced anxiety and depression-like symptoms were paralleled by a decreased in whole-brain OXT levels." (PMID 33875712, 2021). "Here we demonstrate that pharmacological manipulation of the OXT system during the early postnatal period (P1-P5) improves social and anxiety-like behaviours, as well as the immune response later in life in the C-section mice model." (PMID 34040156, 2021). "As a consequence, there is a growing interest in translating OXT neuroscience into a potential treatment for psychiatric conditions ranging from anxiety to autism spectrum disorders, depending on the specific dysfunction that is targeted with OXT." (PMID 32981445, 2021). "OXT also has an important role in modulating synaptic plasticity and stress-related disorders such as depression and anxiety, which are very widespread in developed countries." (PMID 32438751, 2020). "If this were indeed the case, we would expect that changes in endogenous OXT mediate behavioral changes, and that imitation leads to another major OXT effect on behavioral state, namely decreased anxiety or stress, and an increased sense of well-being." (PMID 33071856, 2020). "Peripheral administration of OXT has antidepressant effects, and has also been shown to exert the opposite effects on anxiety behavior." (PMID 32719656, 2020). "Together these findings support a regulatory role of OXT on anxiety‐related processing and further emphasize the context‐ and person‐dependent effects of intranasal OXT." (PMID 32832361, 2020). "The role of OXT pathway in favoring pro-social behavior and reducing anxiety has led to propose the administration of OXT as a potential treatment for autism, particularly through intranasal delivery." (PMID 32546261, 2020). "OXT central activity, mediated through the amygdala and the anterior cingulate, plays a central role in human social behavior, social cognition, anxiety, mood regulation, stress modulation, and fear learning and extinction." (PMID 32824625, 2020). "We demonstrated that otpa−/− mutants exhibit deficits in social- and anxiety-related behaviors, which are correlated with expression of OXT as well as neuropeptide switching in a new cluster of OXT neurons located in the PT." (PMID 28094761, 2017). "Lower endogenous OXT levels are associated with impaired social cognition in various mental diseases including ASD, schizophrenia, and anxiety." (PMID 28566999, 2017). "Control and CSS-exposed F1 dams were administered IN saline, AVP, or OXT during lactation and the F2 juvenile female offspring were assessed for basal plasma IFNγ and perseverative, anxiety, and social behavior." (PMID 28018290, 2016). "Both maternal AVP and OXT are effective at preventing social stress-induced increases in self-directed measures of anxiety, and AVP is particularly effective at preventing impairments in overall social contact." (PMID 28018290, 2016). "Motherhood also involves behavioral changes, such as long-term memory of mothering mediated by OXT and selectively reduced stress responses and anxiety." (PMID 24616713, 2014). "Early attempts to reconcile different effects of OXT on social behavior suggested interaction effects between stress, anxiety and social approach." (PMID 24596548, 2014). "Given the well-known role of OXT in facilitating pro-social behaviors and reducing anxiety-like behaviors, we expected to find a facilitating effect of OXT on social play, especially in the novel cage." (PMID 24982623, 2014). "A variety of behaviours, including maternal care and aggression, pair bonding, sexual behaviours, social memory, and support, as well as anxiety-related behaviour and stress coping, are modulated by brain OXT." (PMID 22997507, 2012).
Anxiety (continued). "This hypothesis was recently proven by using the 3,4-methylenedioxymethamphetamine stimulation tests and identifying OXT deficiency in patients with AVP-D, linked to increased anxiety and impaired emotion recognition." (PMID 42082227, 2026). "Furthermore, these animals display decreased levels of key neuropeptides such as OXT, orexin, and AVP—peptides associated with anxiety-like behavior, altered energy homeostasis, and autonomic dysfunction." (PMID 41516228, 2025). "For example, the modification of estrogen receptor beta function by female reproductive hormones in the PVN promotes the production of OXT mRNA, leading to additional decreases in anxiety-like behavior and dampening of stressed-triggered corticosterone responses." (PMID 40262904, 2025). "While OXT is known to play a modulatory role in anxiety behaviour, stress responses and social behaviour, the effects of exogenous OXT are still variable and the brain regions that transmit OXT signals from the PVN for proper execution of behaviour have not fully been identified." (PMID 40858267, 2025). "Therefore, the data demonstrate a circuitry role for PVN OXT signalling in the expression of prosocial and anxiety-related behaviour and reveal a possible OXT mechanism underlying behavioural deficiency in BTBR mice as an ASD mouse model." (PMID 40858267, 2025). "Notably, feeding-related genes (AgRP, NPY, OXT) and those involved in regulating stress and anxiety (DOR and MC3R) were differentially regulated in the VPA rats." (PMID 40004532, 2025). "Neumann and Slattery hypothesised that individuals who have higher levels of OXT are less likely to experience stress-related disorders such as depression and anxiety." (PMID 40559398, 2025). "Although this observation is restricted to the social domain, the mechanism may also extend to stress-triggered OXT signaling in the amygdala due to its well-known role in stress and anxiety-like behavior." (PMID 40262904, 2025). "Oxytocin (OXT): Best known for its role in uterine contractions during labor and in lactation, OXT, a nine-amino-acid neuropeptide regulates social behaviors such as including social attachment, social cognition, anxiety, aggression, and immune functioning." (PMID 41149794, 2025). "This indicates that E2 treatment may interact with OXT in the body to mediate anxiety-like behavior, particularly in DEHP-exposed females." (PMID 39839474, 2024). "As we found strain-specific differences in OXTR binding, we further evaluated, whether icv OXT can at least partially ameliorate the differences in anxiety-related and social behavior between adult BL6 and CD1 mice." (PMID 39717700, 2024). "Based on our behavioral studies and the altered OXT system in BL6 mice, we consequently investigated, whether acute icv OXT infusion exerts beneficial effects on anxiety-like and social behavior, especially in adult BL6 mice." (PMID 39717700, 2024). "Anxiety, stress, and social stimuli can all induce the synthesis and release of OXT in the brain." (PMID 39295107, 2024). "The OXT/OXTR system mediated anxiety-like behavior and response to stress in mammals." (PMID 37153633, 2023). "The behavioral effects of chronic OXT were paralleled by activation of an intracellular signaling pathway, which ultimately led to alternative splicing of hypothalamic corticotropin-releasing factor receptor 2α (Crfr2α), an important modulator of anxiety." (PMID 34035479, 2023). "Specifically, rs2254298 GG carriers with AUD may have higher OXTR methylation, lower OXT levels, less secure attachment, and higher anxiety levels during alcohol withdrawal." (PMID 37520225, 2023). "Moreover, the OXT system in the central nervous system (CNS) plays important roles in social recognition, social behaviors, anxiety-related behaviors, and autonomic functions, such as maternal behavior, aggression, mating, attachment, and sexual behavior." (PMID 37153633, 2023).
Anxiety (continued). "However, we and others have found adverse effects on anxiety, fear, and social behaviors after chronic OXT application, or otherwise artificially enhanced OXT signaling, in rodents." (PMID 34035479, 2023). "As in previous studies, we also measured effects of OXT on reducing state anxiety." (PMID 36389233, 2022). "The observed sex difference in OXTR methylation could be explained with different functions of OXT in females versus males, for instance, as it has been described for the regulation of anxiety-related and social behaviors." (PMID 36042529, 2022). "This may link the observed interactive effects to overarching theories on the regulatory role of OXT on stress- and anxiety-related processes." (PMID 35723242, 2022). "Interestingly, recent studies in mammalian models have demonstrated that OXT neurons can also be negatively reinforcing, and promote fear, stress, and anxiety in some situations." (PMID 35545618, 2022). "Overall, our findings suggest that oral administration of OXT produces similar effects on top-down social attention control and anxiety to intranasal administration and may therefore have therapeutic utility." (PMID 36053298, 2022). "The present study shows that a significant increase of brain OXT levels following FLX + EE exposure could conceivably decrease anxiety and depression-related behaviors by reducing HPA axis function in stressed postpartum dams." (PMID 33875712, 2021). "Interestingly, FLX + EE was related to decreased anxiety and depression-like behaviors and increased brain OXT levels." (PMID 33875712, 2021). "Very interestingly, prenatal OXTR deficiency potentiates maternal diabetes-mediated anxiety-like behavior while again having little effect on ALB, which is consistent with previous findings that OXT is associated with anxiety, but not necessarily with ALB." (PMID 33633538, 2021). "Indeed, intranasal administration of synthetic OXT in healthy subjects reduces anxiety levels and promotes various aspects of human social behaviors." (PMID 34576161, 2021). "Collectively, we report functional roles of septal OXT signaling in the regulation of anxiety and identified the involved downstream target, which might serve as a target for therapeutic interventions in minimizing unintended side effects of OXT." (PMID 34489531, 2021). "Finally, some authors have shown that OXT is not only involved in early bonding between children and caregivers, but also in anxiety due to separation of emotional ties in young people." (PMID 34805562, 2021). "OXT, which was originally known to stimulate labor and milk ejection during female reproduction, is a neuropeptide hormone that plays roles in maternal care, social recognition, stress regulation, mood and anxiety." (PMID 31251738, 2019). "However, in both tests, co-administration of OXT (0.5 μg) with V1aRA (1 μg) attenuated isolation-induced depression and anxiety-related behaviors." (PMID 30158853, 2018). "Both VP and OXT together with their receptors also affect sexual behaviors such as pair bonding and preference for monogamous pairing as well as mate guarding, social bonding and recognition, aggression, stress, and anxiety." (PMID 29576676, 2018). "We aimed to determine whether OXT was involved with isolation-induced behavioral abnormalities such as depression and anxiety-related behaviors and whether OXT acts on the CeA that contains abundant expression of OXTR." (PMID 30158853, 2018). "We therefore explored whether intra-CeA injection of OXT reduced isolation-induced depression and anxiety-related behaviors in isolated mice." (PMID 30158853, 2018). "In addition, we have reported that CD157 knockout (Cd157−/−) mice display severe anxiety-related and depression-like behaviors or social avoidance that were reversed upon treatment with anti-depression drugs and OXT." (PMID 28566999, 2017).
Anxiety (continued). "It was hypothesized that maternal AVP and OXT treatment would have preventative effects on social stress-induced deficits in offspring anxiety and social behavior and that these effects would be associated with changes in interferon-γ (IFNγ)." (PMID 28018290, 2016). "While AVP and OXT have been reported to have similar effects on anxiety and social behavior in some species, the present results support the hypothesis that they have unique, behaviorally specific programing effects on offspring." (PMID 28018290, 2016). "However, HFS of PVNOXT neurons displayed a LTP of AMPAR‐mediated synaptic transmission of PVNOXT neurons and could reverse cSD‐induced anxiety by promoting the OXT‐mediated inhibitory transmission of the mPFC." (PMID 40468614, 2025). "OXT is known to have stress-protective and anxiolytic effects and low levels of OXTR expression in brain regions responsible for emotional and social behaviors are hypothesized to be associated with high anxiety levels." (PMID 38645599, 2024). "Given OXT’s anxiolytic properties and the reported potential to decrease withdrawal, whether its effects on alcohol consumption are mediated by decreases in anxiety-like and withdrawal-like behaviors could be examined." (PMID 36369481, 2023). "The present results confirm that the release of OXT can be conditioned to emotional states, in our case, to anxiety, and the actions of this peptide may provide an additional explanation for the short- and long-term benefits of positive contact and vocal experiences in the NICU." (PMID 36832462, 2023). "Finally, we hypothesized that orally administered OXT would produce a similar profile of increased concentrations in blood as lingual administration and would reduce state anxiety similar to both intranasal and lingual OXT." (PMID 36389233, 2022). "Similarly, preclinical research has revealed that injections of OXT (1 ng/200 nL) into the NAc shell reverses the alterations in social behavior, anxiety, and depressive symptoms induced by chronic SD, while injections of an antagonist blocks the effects of OXT in female mandarin voles." (PMID 33673448, 2021). "Taken together, these results support the hypothesis that maternal AVP and OXT treatment have context- and behavior-specific effects on peripheral IFNγ levels and perseverative, anxiety, and social behaviors in female offspring of early-life social stress-exposed dams." (PMID 28018290, 2016). "In a chronic social stress (CSS) mediated rodent model of PPD, OXT gene expression is reduced in the hypothalamus and amygdala of stress exposed rats that exhibit depressed maternal care, impaired lactation, and increased anxiety, and OXT levels in the amygdala are correlated with maternal care." (PMID 27617302, 2015). "Interestingly, some rodent studies provide evidence suggesting that OXT in the lateral septum may reduce pro-social behaviors and enhance anxiety." (PMID 24982623, 2014). "Given that AVP and the closely related neuropeptide oxytocin (OXT) modulate social behavior as well as anxiety-like behavior, we hypothesized that these neuropeptides may regulate social play behavior differently in novel (novel cage) as opposed to familiar (home cage) social environments." (PMID 24982623, 2014). "Moreover, given lactation-associated anxiolysis, and the role of both OXT and MAPK in anxiety, this pathway may be necessary for this effect." (PMID 22615888, 2012). "Intermittent 1.5 mA EA at Baihui (GV20) mitigates anxiety-like behavior in mice via a PVN-derived, OXT-dependent pathway." (PMID 41530867, 2026). "Specifically, OXT has been shown to reduce the activity of the hypothalamic–pituitary–adrenal (HPA) axis and mitigate anxiety-like behaviors during physiological and psychological stress." (PMID 40262904, 2025). "Our present data extend the OXT circuit defects in BTBR mice to the control of prosocial and anxiety-like behaviours." (PMID 40858267, 2025).
Anxiety (continued). "Interestingly, short‐term high‐frequency stimulation (HFS) of PVNOXT neurons displayed a long‐term potentiation of AMPAR‐mediated synaptic transmission of PVNOXT neurons and could reverse cSD‐induced anxiety by promoting the OXT‐mediated inhibitory transmission of the mPFC." (PMID 40468614, 2025). "While OXT is mainly involved in performing social behaviour, CRH is largely involved in regulating stress and anxiety." (PMID 40559398, 2025). "This method effectively isolates mice socially, exacerbating anxiety and depression, and affects neuropeptide levels (e.g., AVP, OXT), even in naïve mice." (PMID 38474180, 2024). "However, in mice, the alterations in anxiety-behavior were described to be controversial, with elevated stress response in mild stress model, which may dependent on the instability of behavior of rat or the dose of OXT (chronic i.c.v OXT injection)." (PMID 38017588, 2023). "In conclusion, chronic central infusion of high OXT results in MEF2A activation in the PVN of male rats, and increased anxiety-related behavior." (PMID 34035479, 2023). "OXT, in conjunction with oxytocin receptor (OXTR), has been reported to play an important role in regulation of social recognition and anxiety-like behaviors as well as many other kinds of pathophysiological processes." (PMID 35370982, 2022). "Given that anxiety and depression are highly comorbid pathologies in humans, we tested whether mice born by C-section exhibit depressive-like behaviour using the forced-swim test, as well as, the potential for early-life treatment with OXT to exert anti-depressive response in mice." (PMID 34040156, 2021). "Two studies in mice that were either socially isolated or with deleted OXT-gene, reported significant down-regulation of OXTR in the central amygdala or increased immunoreactivity in amygdala and subsequent exacerbated anxiety-related behaviors." (PMID 32485966, 2020). "Some studies have reported a potential or direct relationship between of the OXT/OXTR signaling system and social recognition, object recognition, object location memory, anxiety behavior, fear-related behavior, and depressive behavior." (PMID 32719656, 2020). "Taken together, these findings suggested that OXT acted specifically on the CeA via OXTR to modulate depression and anxiety-related behaviors." (PMID 30158853, 2018). "CSS offspring also displayed increased perseverative and anxiety behavior, impaired social behavior, and behavior-specific responses to both maternal AVP and OXT treatment." (PMID 28018290, 2016). "Because AVP typically enhances while OXT reduces anxiety-like behaviors of rats exposed to novel environments, we predicted that AVP would reduce social play while OXT would increase social play in the novel cage." (PMID 24982623, 2014). "In addition, OXT can modulate the activity of the HPA axis, counteracting the effects of stress, and alleviating fear and anxiety." (PMID 39607552, 2024). "As reviewed above, the OXT/OXTR system regulates social cognition, social behaviors, emotions, and autonomic functions, including social memory, maternal behavior, attachment, mating, sexual behavior, depression, anxiety, aggression, and others." (PMID 37153633, 2023). "After high chronic OXT treatment, we found distinct alterations in gene expression of closely related genes, of which those of membrane-bound and soluble CRFR2α were particularly striking, because of the known OXT and CRF interactions, as well as the involvement of CRF in stress and anxiety." (PMID 34035479, 2023). "Anxiety, stress, and positive or negative stimuli drive the synthesis and release of OXT and AVP from neurons in the hypothalamic supraoptic nucleus (SON), paraventricular nucleus (PVN), or limbic system regions." (PMID 36430254, 2022). "OXT and AVP are also critical regulators of anxiety and depression-like behaviors." (PMID 36430254, 2022).